GJB6 (gap junction protein beta 6)
Diseases named in the same sentence as GJB6 in open-access papers (continued):
Sharing a sentence is not in itself a finding about the gene and the disease.
hearing loss (continued). "Indeed, mutations in other connexin genes, such as GJB6 for Cx30 and GJB3 for Cx31, have been identified and shown to cause hearing impairment." (PMID 19744334, 2009). "Variants of the gap junction protein beta-2 (Gjb2) and gap junction protein beta-6 (Gjb6) genes, encoding connexin 26 (Cx26) and connexin 30 (Cx30), respectively, have been linked to the deafness DFNB1, the most frequent non-syndromic hearing loss in the Mediterranean population." (PMID 36829891, 2023). "However, recent data including the use of mouse models has indicated that mutations in the coding region of the GJB6 gene do not result in hearing impairment." (PMID 32012697, 2020). "Variants in the GJB6 gene are no longer considered as causes of hearing impairment." (PMID 32012697, 2020). "Although many genes have been associated with hearing loss, mutations in the DFNB1 locus are to be the most frequent cause of autosomal recessive hearing loss and routine sequencing of the GJB2 gene and testing of GJB6 gene deletions are recommended in EMQN best practice guidelines." (PMID 26896187, 2016). "We reviewed the available studies on the aetiology and genetics of hearing loss in Africa, including our previous publications on this topic that have shown the non-implication in Africansof the genes most commonly associated with ARNSHL among patients of European and Asian descent: GJB2 and GJB6." (PMID 26185573, 2015). "We performed a genetic screening of GJB2 gene (responsible for the major etiologies of hereditary hearing impairment among Romanians), GJB3, GJB6, POU3F4 and WFS1 genes." (PMID 33333757, 2020). "In most regions, even basic screenings like GJB2/GJB6 are not available, and worse, numerous individuals with hearing impairment lack access to proper rehabilitation or genetic services." (PMID 38397168, 2024). "Our findings support previous reports that GJB2 and GJB6 do not play a significant role in non-syndromic hearing impairment in most populations of African descent." (PMID 31731535, 2019). "Although molecular analysis of hearing loss is not frequent in developing countries, it is essential to investigate GJB2 and GJB6 gene mutations for public health and genetic counseling purposes." (PMID 20835527, 2010). "Thus, the GJB6 gene itself plays no role in the development of hearing impairment but the surrounding sequences consisting of the cis-acting elements are responsible for the development of hearing impairment." (PMID 32012697, 2020).
deafness (78 papers, 2005 to 2025). An inherited or acquired condition characterized by the complete loss of the ability to hear from one or both ears. "The exact global prevalence of deafness caused by two pathogenic variants involving GJB6 is difficult to estimate." (PMID 40504319, 2025). "These cells expressed several causal genes for various deafness forms, including Eps8l2, Gjb2, Gjb6, Homer2, Coch, Clic5, Dcdc2a, Pou3f4, Col4a6, and Six1." (PMID 37339214, 2023). "Despite not being direct homologs, expression and mutant analyses have found that zebrafish gjb8 and human GJB2/GJB6 genes are all involved in inner-ear support cell function and loss of these genes in their respective systems causes deafness." (PMID 35325106, 2022). "So far, CNVs have been reported in 29 non-syndromic HL-related genes, with STRC, OTOA, and GJB2/GJB6 being the most well-known genes with deafness-causing CNVs." (PMID 35710363, 2022). "These deletions remove all or part of the GJB6 gene, or regions neighboring it, and cause deafness when present in homozygosis or in heterozygosis in combination with a recessive mutation in the GJB2 gene." (PMID 33839059, 2021). "They reported that three SNPs (rs3751385, rs7994748, and rs7329857) related to GJB2 gene and one SNP (rs7333214) related to GJB6 gene showed a significant relationship with deafness (OR>1) and a high risk of ARNSHL (OR=11.7) for rs7329857." (PMID 33912482, 2021). "Mutations in GJB2 and GJB6 cause a wide variety of phenotypes resulting in pre- or post-lingual hearing loss ranging from mild to profound deafness." (PMID 33193034, 2020). "For example, the digenic interaction that underlies the cause of deafness in individuals carrying a single mutation at the GJB2 locus along with a deletion in the functionally related GJB6 gene." (PMID 31898538, 2020). "Mutations in the connexin GJB2 and GJB6 genes, encoding respectively CX26 and CX30, cause syndromic and non-syndromic deafness." (PMID 32098144, 2020). "This region is located between GJB2 and GJB6, two prominent deafness genes, where GJB2 is associated with approximately 30–50% of cases of deafness." (PMID 30478432, 2018). "Until recently, deafness caused by GJB6 (Cx30) deletion was believed to be due to defective Cx26 expression, and Cx30 was considered dispensable for cochlear function." (PMID 28513246, 2017). "Mutations in the connexin genes GJB2 and GJB6 (encoding CX26 and CX30) result in syndromic and non-syndromic deafness via various mechanisms." (PMID 25381570, 2015). "Apart from GJB2 mutations, one kind of deafness-causing GJB6 mutation (⊿GJB6-D13S1854 or 232 kb del) was identified in 5 of 135 hearing-impaired individuals." (PMID 23554706, 2011). "The deafness of individuals heterozygous for GJB2 mutations has been associated with in trans heterozygosity for GJB6 gene deletions." (PMID 21119891, 2010). "The GJB6 deletion and the common non-syndromic deafness-causing mitochondrial mutations were also tested when appropriate." (PMID 15790391, 2005). "In addition, we identified potentially novel deafness-associated genes Mpzl2 in IMCs and Tbx1 in MCs along with the known deafness-associated genes in IMCs (Kcnj10, Met, Mitf, Gjb6, Ednrb, and Gjb2) and in MCs (Kcnq1, Esrrb, Kcne1, Lrp2, Slc22a4, and Hgf)." (PMID 37322474, 2023). "Assessment of the GJB2 and GJB6 gene expressions may improve our understanding of the function of different cellular networks in the human cochlea (HC) and how cell-specific changes and mutations may interact and cause Cx26/Cx30-based deafness." (PMID 36204137, 2022). "The GJB6 gene was first described as a causative in a rare dominant form of deafness, DFNA3, and its implication in NSHL were ascertained through the identification of two large deletions, del(GJB6-D13S1830) of size 309 kb and del(GJB6-D13S1854) of size 232 kb, which truncate the GJB6 gene." (PMID 29921236, 2018).
deafness (continued). "Gjb6 has also been linked to human deafness, although the deleterious effects of Gjb6 knockdown in mice are less severe than those of Gjb2 and may be partly caused by associated downregulation of Gjb2." (PMID 29073148, 2017). "Thus, the cause of deafness after GJB6 deletion is the low expression of GJB2 due to the co-deletion of its putative regulatory element." (PMID 24957570, 2015). "Digenic interactions are known to be an important cause of deafness in patients who carry a single mutation at the gap junction protein GJB2 (connexin 26) along with a deletion involving the functionally related GJB6 (connexin 30)." (PMID 21119891, 2010). "Common causes of deafness in SCs include mutations in genes encoding gap junction proteins, such as GJB2 (Connexin 26), GJB6 (Connexin 30), and GJB3 (Connexin 31)." (PMID 39722701, 2024). "In terms of nearby genes—including the deafness- and cataract-associated connexins (GJA3, GJB2, and GJB6) —we found significantly reduced expression of only GJB6 (log2fc = −1.06, p = 3.47 × 10−4)." (PMID 37239394, 2023). "Because large deletions in the GJB2 or GJB6 gene exhibit a digenic mode of inheritance in the induction of deafness in humans, double Cx26+/−/Cx30+/− heterozygous mice have been established for mechanism research." (PMID 35457072, 2022). "The inner ear sensory epithelium methylomes analysis underpins a low methylated region (LMR) as the regulator of GJB6, a critical gene of deafness." (PMID 35352419, 2022). "To uncover the roles of nuclear gene mutations in deafness, we screened for the mutations in common deafness-associated genes (GJB2, GJB3, GJB6 SLC26A4 and TRMU) in the matrilineal relatives of the HZD055 and HZD510 pedigrees." (PMID 36292680, 2022). "In a study conducted in Iran, OR values were reported as 2.45 and 0.43 for GJB2 and GJB6 genes, respectively; accordingly, the possibility of deafness increased, compared to that reported for the control group." (PMID 33912482, 2021). "To examine the roles of nuclear genes (GJB2, GJB3, GJB6 and TRMU) in the phenotypic manifestation of deafness-associated 12S rRNA mutations, we carried out a mutational screening of these genes in affected matrilineal relatives of three pedigrees." (PMID 32400865, 2020). "In other words, deafness can be caused by the addition of a mutation in one allele of GJB2 and one allele of GJB6 or GJB3, indicating an interaction of these connexins in the cochlea." (PMID 33126609, 2020). "Subsequently, 75 Cameroonian patients with non-syndromic deafness were analyzed through direct Sanger sequencing of the entirety of the coding regions of GJB6 gene and GJA1 pseudo-gene; the large-scale GJB6-D3S1830 deletion was also investigated." (PMID 32098311, 2020). "It is has been shown that digenic inheritance of recessive deafness by mutations in GJB2 and GJB6, or GJB2 and GJB3 can occur." (PMID 33126609, 2020). "In our series, as in most of published studies, prior to comprehensive genetic testing, patients were prescreened for common deafness mutations (in our cohort, GJB2/GJB6, OTOF and MT-RNR1, selected for their high prevalence in Spain)." (PMID 29986705, 2018). "In this present study we have used an allele-specific PCR-based universal array designed to simultaneously screen nine deafness associated variants in the GJB2, GJB6, SLC26A4, MT-RNR1 and MTTS genes that are common in patients of European descent." (PMID 28273078, 2017). "There are significant differences in the clinical picture of two rare autosomal dominant syndromes: keratitis–ichthyosis–deafness (KID) syndrome and hidrotic ectodermal dysplasia (Clouston syndrome), which are caused by GJB2 and GJB6 mutations, respectively." (PMID 25575739, 2015). "In fact, digenic inheritance of nonsyndromic deafness caused by mutations in the GJB2 gene and other connexin genes, such as GJB3, GJB6, GJB4, or GJA1, have been previously reported in several deaf patients." (PMID 25388789, 2014).
deafness (continued). "In summary, current data revealed that near half of the patients with NSHL carry deafness-causing mutation in GJB2, GJB3, GJB6, SLC26A4, or mtDNA 12SrRNA genes: 43.57% in China and 50.06% in other countries." (PMID 23554706, 2011). "The carrier frequencies of deafness-causing mutations in these patients were 35.55% in GJB2, 3.70% in GJB6, 15.56% in SLC26A4 and 8.14% in mitochondrial 12SrRNA, respectively." (PMID 23554706, 2011). "Notably, large deletions in the GJB2 or GJB6 gene correspond with a monogenic or digenic mode of inheritance and induce deafness either in a homozygous or heterozygous state." (PMID 35457072, 2022). "More than 300 deafness mutations have been reported in GJB2 and GJB6." (PMID 35573684, 2022). "Furthermore, in Brazil, OR values of 11.7 and 0.46 were reported for GJB2 and GJB6 genes for the possibility of deafness, respectively, which increased in comparison to those of the control group." (PMID 33912482, 2021). "In addition, the analysis provides the basis for an expanded view of the regulatory mechanism of GJB6, a critical gene in human deafness." (PMID 30478432, 2018). "While the GJB2 gene mutations associated with skin symptoms all cause deafness, mutations in the GJB6 gene result in skin disease, usually without hearing impairment." (PMID 25575739, 2015). "Observations made from the first Gjb6 knock-out mouse model led to the mistaken conclusion that inactivation of Gjb6 alone could lead to deafness." (PMID 24957570, 2015). "Further, the authors propose that dominant GJB6 deafness mutations manifest themselves via their negative effects on heteromeric channels comprising normal Cx26 and mutated Cx30, and large deletions of GJB6 affect GJB2 expression." (PMID 25381570, 2015). "Taken together, these results suggested that GJB2 and GJB6 expression is interrelated at the transcription and translation levels in the cerebellum and cochlea, which may be regulated through the NF-κB pathway and contribute to deafness." (PMID 37178259, 2023). "Moreover, the present study could be conducted on other genes of deafness or other polymorphisms, including rs3751385, rs7994748, and rs7987302 of GJB2 gene and rs7322538, rs9315400, rs877098, and rs945369 of GJB6 gene." (PMID 33912482, 2021). "About molecular analysis, individuals with deafness of unknown etiology and who lived in the Midwest state of Minas Gerais, Brazil, were investigated for the presence of 35delG and D13S1830 mutations in GJB2 and GJB6 respectively." (PMID 30837189, 2020). "Thus, deafness-causing variants in the genes underlying Connexin-related deafness (GJB2 and GJB6, also sometimes referred to as Connexin-26 and Connexin-30, respectively) appear to play a significant role in the history and formation of the Deaf community and Deaf culture in the United States." (PMID 25375116, 2014). "GJB2 gene mutations, GJB6 deletion, and the A1555G mitochondrial mutation play a major role worldwide in causing deafness, but there is a high degree of genetic heterogeneity and many genes involved in deafness have not yet been identified." (PMID 24312468, 2013). "GJB6 (OMIM No. 604418) encoding connexin 30 (Cx30) was an obvious candidate gene for deafness owing to its chromosomal location at 13q12, and because connexin 26 and connexin 30 are expressed in the same inner ear structures and share 77% homology in amino acid sequence." (PMID 23554706, 2011). "Five prominent deafness-related genes, GJB2, SLC26A4, GJB6, POU3F4, and mtDNA 12S rRNA, were analyzed." (PMID 22389666, 2012). "Interestingly, among others PSMC3 was shown to interact with CHMP4B (MIM 610897), ACTG1 (MIM 102560) and GJB6 (MIM 604418) involved in cataract and deafness." (PMID 32500975, 2020). "Cx30 homozygous knockout-LacZ mice (Gjb6tm1Kwi/Gjb6tm1Kwi; MGI:2447863; EM:00323), hereafter abbreviated as Cx30−/−, are a model for humans in which large deletions in the DFNB1 locus lead to downregulation of both GJB2/CX26 and GJB6/CX30 and profound deafness." (PMID 33569381, 2020).
deafness (continued). "We further verified that the hearing loss could be accounted for by the p.V37I allele of GJB2, and not by other known deafness genes by targeted next generation sequencing (panel sequencing) of 82 known deafness genes (including GJB2, GJB3 and GJB6)." (PMID 23637863, 2013). "However, the lack of any functional variants in GJB2, GJB3, GJB6 and TRMU suggested that nuclear genes may not play active roles in deafness expression." (PMID 32400865, 2020). "Some deletions impact only one other connexin gene, the GJB6 gene, but studies have described that DFNB1 deafness is not due to the GJB6 deletion but the dysregulation of GJB2 expression." (PMID 35805969, 2022). "Here, we investigate the genetic etiology of deafness in two GJB2 and GJB6 negative patients presenting with pre-lingual, progressive, severe hearing loss." (PMID 33530996, 2021).
Clouston syndrome (22 papers, 2009 to 2026). "The paw pad hyperkeratosis phenotype in the investigated dog shows similarities to Clouston syndrome and strongly suggests that the GJB6 missense variant is responsible for its condition." (PMID 41601192, 2026). "Different mutations in GJB6 (Cx30) can cause Clouston syndrome in humans, a rare autosomal dominant genetic disorder characterized by alopecia, nail dystrophies, and palmoplantar hyperkeratosis, among other pathologies." (PMID 39313816, 2024). "The other case presented is that of a family with Clouston syndrome (caused by p.Gly11Arg mutation in GJB6), who are the first reported patients of Polish origin suffering from this disorder." (PMID 25575739, 2015). "The results of DNA analysis in the three patients confirmed the clinical diagnosis of KID syndrome in patient 1 [heterozygous mutation p.Asp50Asn (c.148G>A) in GJB2] and Clouston syndrome in patients 2 and 3 [mutation p.Gly11Arg (c.31G>C) in GJB6]." (PMID 25575739, 2015). "Mutations in the GJB6 gene, encoding Cx30, are responsible for Clouston syndrome." (PMID 38827992, 2024). "The amino acid N14 is near two of the residues mutated in Keratitis-like ichthyosis deafness (KID) syndrome (p.G12R and p.S17F), yet the phenotype associated with p.N14K strongly differs from the KID phenotype, having a phenotype more similar to Clouston syndrome (caused by mutations in GJB6)." (PMID 22547955, 2011). "Four diseases, including clouston syndrome or hidrotic ectodermal dysplasia (HED), have been linked to variants of GJB6, a gene located just 30 kb telomeric to GJB2 on chromosome 13." (PMID 29018324, 2017). "Two rare congenital disorders, keratitis–ichthyosis–deafness (KID) syndrome [OMIM 148210] and Clouston syndrome (hidrotic ectodermal dysplasia 2) [OMIM 129500], are caused by mutations in genes coding connexin proteins (GJB2 and GJB6, respectively), and both of them have skin manifestation." (PMID 25575739, 2015).
glioma (13 papers, 2015 to 2025). A benign or malignant brain and spinal cord tumor that arises from glial cells (astrocytes, oligodendrocytes, ependymal cells). "Research had announced that the levels of GJB6 were also decreased during the development of cancers, including gastric cancer, gliomas and head and neck cancer." (PMID 35774610, 2022). "In glioma, GJB6 (encoding Cx30) was deleted in 25.8% of the 751 analysed tumours and was mutated in 15.8% of 158 tumours." (PMID 30814684, 2019). "Specificity of expression for connexin genes in astrocytic cells, GJA1/Cx43, GJB6/Cx30, and GJB2/Cx26, was used to verify expected cells of origin for the glial tumors, oligodendrogliomas, and glioblastomas in REMBRANDT patients on anti-seizure drugs." (PMID 40867621, 2025).
KID syndrome (9 papers, 2011 to 2026). Keratitis (and hystrix-like) ichthyosis deafness (KID/HID) syndrome is a rare congenital ectodermal disorder characterized by vascularizing keratitis, hyperkeratotic skin lesions and hearing loss. "In very rare cases, KID syndrome can be caused by mutations in the gap junction protein beta 6, GJB6 (connexin 30)." (PMID 38835422, 2023). "KID syndrome could be caused by heterozygous dominant missense mutations in GJB2 (gap junction protein beta 2) and GJB6 (gap junction protein beta 6) genes, encoding connexin 26 (Cx26) and Cx30, respectively." (PMID 32054030, 2020).
sensorineural hearing loss (9 papers, 2010 to 2025). "Among the main genetic defects, mutations within connexin 26 (GJB2) and connexin 30 (GJB6) are usually associated with severe to profound sensorineural deafness." (PMID 26323392, 2015). "The GJB2 (connexin 26) and GJB6 (connexin 30) genes, both at the DFNB1 locus, are most commonly associated with bilateral sensorineural hearing loss, accounting for up to 31% of genetic cases confirmed in a recent study." (PMID 36529647, 2022). "To evaluate the added diagnostic value of this microarray for our ethnically diverse patient population, we tested 144 individuals with congenital sensorineural hearing loss who were negative for biallelic GJB2 or GJB6 mutations." (PMID 20668687, 2010). "Thus, this study aimed to investigate and describe the prevalence of mutations in the SLC26A4 gene in nonsyndromic prelingual sensorineural hearing loss (SNHL) patients of a cohort from the Southeast of Brazil who had been previously tested for GJB2, GJB6, and MT-RNR1." (PMID 30068397, 2018).